TTK (TTK protein kinase)
Diseases named in the same sentence as TTK in open-access papers (continued):
Sharing a sentence is not in itself a finding about the gene and the disease.
pancreatic cancer (20 papers, 2016 to 2025). "Previous studies have revealed that a high expression of TTK is associated with a poor prognosis for EC, liver cancer, and pancreatic cancer." (PMID 34616422, 2021). "Interestingly, mutations in the TTK gene were observed in CRCs with microsatellite instability, and its role is closely related to pancreatic cancer cell proliferation and malignant transformation." (PMID 27635108, 2016). "Meanwhile, recent studies have shown that the promoter of TTK is regulated by H3K18 lactylation in pancreatic cancer, the regulatory mechanisms of upstream transcription and activation of TTK in TCL remains to be further investigated." (PMID 39836493, 2025). "H3K18 lactylation in pancreatic cancer cells promotes the expression of TTK/BUB1B kinase, which subsequently upregulates LDHA, leading to increased lactate production." (PMID 40755753, 2025). "In pancreatic ductal adenocarcinoma (PDAC), TTK knockdown substantially reduced proliferation and increased apoptosis in cell lines, highlighting its role in pancreatic cancer growth." (PMID 38195567, 2024). "Numerous studies have demonstrated the carcinogenic effects of TTK in various human cancers, including triple-negative breast cancer, pancreatic cancer, and hepatocellular carcinoma." (PMID 38195567, 2024). "Silencing of TTK in PCa, gastric and pancreatic cancer cells inhibited cell proliferation, invasion and migration, and increased apoptosis." (PMID 34366863, 2021). "Eight genes (BUB1, BUB1B, CCNA2, CCNB2, CDC6, CDC20, CDK1, and TTK) among 21 common network genes were correlated with worse survival of pancreatic cancer, highlighted with P-value significantly <0.05." (PMID 32117719, 2020). "Taken together, our results suggest a critical role for TTK in preventing aneuploidy-induced cell death in pancreatic cancer." (PMID 28380042, 2017). "For example, ANLN and PRC1 were mutated in cells derived from a malignant melanoma, and RANBP2, TTK, PP2R1A, and CEP192 were mutated in cells from pancreatic cancers." (PMID 27144335, 2016). "For example, the CBP/p300 inhibitor CPI-0610 shows promise in preclinical models of pancreatic cancer by disrupting the lactylation-TTK/BUB1B feedback loop, while HDAC1 agonist entinostat reverses immunosuppression in colorectal cancer by de-repressing CD8+ T cell infiltration." (PMID 40755753, 2025). "Numerous studies have shown that TTK expression is abnormally increased in various types of human malignancies, such as triple-negative breast cancer, pancreatic cancer, and hepatocellular carcinoma, and contributes to cancer promotion and, in some cases, poor prognosis." (PMID 40723362, 2025). "In addition, recent studies have revealed that TTK functions as an oncogene in a variety of cancers, such as glioblastoma, breast, liver, prostate, lung, bladder, gastric, colon and pancreatic cancer, and knocking down TTK expression inhibits tumor growth." (PMID 34876569, 2021). "Another kinase that was inhibited by J54, TTK, may play important roles in mitotic progression and was reported to be critical in pancreatic cancer." (PMID 32905878, 2020). "TTK is regulated in multiple types of cancers, including breast, liver, lung and pancreatic cancer." (PMID 32121246, 2020). "In this study, we showed that mitotic spindle assembly checkpoint regulators TTK and BUB1B were highly expressed in human pancreatic cancer tissues and worked as prognostic factors in PDAC, which are in consistent with previous reports." (PMID 38711083, 2024). "Our study delves into the intricacies of nab-paclitaxel resistance in a model of pancreatic adenocarcinoma, PANC-1, and pinpoints the pivotal role played by three SAC proteins—BUB1B, TTK, and BUB3—in determining sensitivity of a pancreatic cancer cell line to paclitaxel." (PMID 38410481, 2024).
colon carcinoma (19 papers, 2006 to 2025). "The selective TTK inhibitor CFI-402257 has anti-cancer effects on human colon cancer cells, causing cell death." (PMID 36829176, 2023). "TTK gene expression is increased in colon tumor tissues compared to normal tissue, which is associated with increased proliferation of cancer cells through the activation of PKCα/ERK1/2 and inhibition of differentiation through inactivation of the PI3K/Akt pathway." (PMID 40723362, 2025). "For colon cancer, one investigation deduced that TTK expression is notably elevated, correlating with adverse patient prognosis and heightened cell proliferation." (PMID 37894942, 2023). "In colonic cancer, TTK, as an oncogene, promotes the proliferation of cancer cells via PKCα/ERK1/2 and PI3K/Akt pathways." (PMID 34516342, 2021). "TTK inhibits the PI3K/AKT pathway, and TTK knockdown inhibits the PKCα/ERK signaling pathway in colon cancer." (PMID 34876569, 2021). "With regard to the stemness-related genes, TTK was reported to regulate colon cancer progression via PI3K/AKT pathway." (PMID 34178686, 2021). "It has been reported that specific inhibitors of TTK, AZ3146 and MPI‐0479605, effectively have been described to inhibit proliferation of hct‐116 colon cancer cells, indicating that TTK is involved in tumor formation." (PMID 32530571, 2020). "In addition to this, it was also reported that different TTK inhibitors, such as AZ3146 and MPI-0479605, can effectively be utilized to inhibit the proliferation potential of hCt-116 colon cancer cells, showing the overexpression of TTK." (PMID 37304238, 2023). "Notably, we have found a strong correlation between HMGA1 and BUBR1 and TTK protein levels in human colon carcinomas." (PMID 26009897, 2015). "Besides, TTK was found to regulate tumor proliferation in gastric cancer, colon cancer and HCC." (PMID 38658569, 2024). "Interestingly, a weak immunoreactivity was observed in normal colon mucosa after staining with antibodies raised versus BUBR1 and TTK, whereas colon carcinoma samples showed a strong immunoreactivity that significantly correlated with HMGA1 staining (p = 0.006 for BUBR1 and p < 0.001 for TTK)." (PMID 26009897, 2015). "Mitotic checkpoint kinase Mps1 (also known as TTK) activates the PKCα/ERK1/2 pathway but inhibits the PI3K/Akt pathway, resulting in the promotion of cell proliferation in colon cancer HT-29 and SW480 cells." (PMID 36358843, 2022). "Conversely, we found that 6 genes involved in the mitotic spindle checkpoint (TTK, BUB1, BUB3, CDC20, MAD2L1, and BUB1B) are overexpressed in colon cancer specimens." (PMID 16919171, 2006). "The up-regulation of TTK can activate PKCa/ERK1/2 to promote the division of colon cancer cells and the lack of TTK can lead to apoptosis." (PMID 34787756, 2022).
prostate carcinoma (19 papers, 2012 to 2025). A carcinoma that arises from epithelial cells of the prostate gland. "TTK expression is also linked to prostate cancer progression, and knockdown of TTK represses the malignancy of prostate cancer cells." (PMID 34516342, 2021). "Genes like TTK show potential as significant targets reported in breast, bladder, and prostate cancers, warranting further investigation of TTK−192 (p = 0.04 in UCEC) as an intriguing hotspot." (PMID 38473427, 2024). "We identified and validated four candidate genes (AKT1, PSMC1, STRADA, and TTK) that impaired growth when silenced in androgen receptor positive prostate cancer cells and enhanced the antiproliferative effects of antiandrogens." (PMID 22509301, 2012). "Similarly, TTK, a mitotic checkpoint kinase and recognized oncogene, is positively correlated with higher Gleason scores in prostate cancer." (PMID 41468516, 2025). "TTK may inhibit the proliferation of prostate cancer and the progression of prostate cancer by inhibiting the expression of CDK2 and CCNE1 complex." (PMID 37682152, 2023). "Other studies also reported elevated expression of TTK in prostate cancer and lung adenocarcinomas." (PMID 37770979, 2023). "The prostate cancer patients with high expression levels of TTK had a shorter time to relapse." (PMID 34187556, 2021). "TTK was previously reported to be highly expressed in prostate cancer and Hodgkin's lymphoma." (PMID 27635108, 2016). "To explore whether AKT1, STRADA, and TTK are altered in human prostate cancer, we assessed the copy number and expression status of these genes in a previously-reported human prostate cancer dataset." (PMID 22509301, 2012).
triple-negative breast carcinoma (19 papers, 2013 to 2026). An invasive breast carcinoma which is negative for expression of estrogen receptor (ER), progesterone receptor (PR), and human epidermal growth factor receptor 2 (HER2). "Elevated TTK expression is associated with aggressive phenotypes in triple-negative breast cancer cells." (PMID 38410481, 2024). "In triple negative breast cancer, overexpression of TTK is associated with tumor progression and prognosis, and its knockdown inhibits cancer cell invasion and proliferation." (PMID 35816352, 2022). "ANAPC4 inactivation confers resistance to multiple TTK protein kinase inhibitors in triple-negative breast cancer." (PMID 38425244, 2024). "In triple-negative breast cancer, increased TTK expression correlates with tumor tropism and metastatic behavior." (PMID 38195567, 2024). "For example, TTK regulates the EMT in triple-negative breast cancer cells and its knockdown led to reduced viability and colony formation ability in MDA-MB-231 and Hs578t cells." (PMID 36568153, 2022). "Dual specificity protein kinases, TTK were involved in the control of the cell cycle program, TTK is considered an important biomarker in liver cancer, triple-negative breast cancer, ovarian cancer, gastric cancer, and colorectal cancer." (PMID 34072728, 2021). "TTK inhibitors increased the efficacy of taxane chemotherapy in patient-derived xenograft models and in an immunocompetent mouse model of triple-negative breast cancer." (PMID 31106147, 2019). "Recently, overexpression of TTK, another checkpoint in mitosis, was reported to occur in triple negative breast cancers, which frequently harbor PD-L1 amplifications." (PMID 29212506, 2017). "TTK mRNA expression is reported to be up-regulated due to copy number variation (CNV) in triple-negative breast cancer." (PMID 26418879, 2015). "A component of the Spindle Assembly Checkpoint, TTK protein kinase whose inhibition could be a novel therapeutic target for the treatment of triple-negative breast cancer (TNBC) and pancreatic ductal adenocarcinoma (PDAC), is overexpressed in several cancers." (PMID 35677427, 2022). "In triple-negative breast cancer and other aggressive cancers of the breast subgroups, the TTK protein is a prognostic marker, and treatment resistance and aggressiveness of the cancer are due to the protection of the CIN caused by proteins like TTK." (PMID 34072728, 2021). "TTK inhibitors, such as BAY 1161909, have demonstrated antitumor activity in clinical trials for triple-negative breast cancer." (PMID 40286596, 2025). "In this study, we examined the role of TTK in triple negative breast cancer (TNBC), and found that higher TTK expression correlated with mesenchymal and proliferative phenotypes in TNBC cells." (PMID 30206215, 2018).
gastric cancer (18 papers, 2011 to 2025). A primary or metastatic malignant neoplasm involving the stomach. "In gastric cancer, high expression of TTK is associated with poor prognosis of the patients, and depletion of TTK suppresses the proliferation and induces the apoptosis of gastric cancer cells via modulating Akt-mTOR signaling." (PMID 34516342, 2021). "By analyzing the survival rate of gastric cancer patients, we also found that the survival rate of cancer patients with TTK mutations was significantly higher than that of cancer patients without TTK gene mutations." (PMID 32530571, 2020). "Our study found that TTK is associated with poor survival and poor prognosis in patients with gastric cancer and is expected to be a potential target for the treatment of gastric cancer." (PMID 32530571, 2020). "The database search revealed 92 gastric cancer patients with TTK mutations with an average survival period of 87 months." (PMID 32530571, 2020). "First, to analyze whether TTK gene mutation is associated with the survival rate and recurrence of cancer patients, we searched for data on gastric cancer patients in the TCGA database." (PMID 32530571, 2020). "Next, we investigated the relationship between TTK mutation gene and gastric cancer recurrence." (PMID 32530571, 2020). "The overall survival rate of patients with gastric cancer was positively correlated with TTK expression, and a high level of TTK overexpression was linked to an increased risk of cancer recurrence." (PMID 39911278, 2025). "Knockdown of TTK inhibited proliferation and increased apoptosis of gastric cancer cells through the Akt-mTOR pathway." (PMID 37815894, 2023). "Survival and tumor recurrence data related to TTK expression levels in gastric cancer patients found TTK expression to negatively correlate with survival and tumor recurrence, while the knockdown of TTK inhibited proliferation and increased apoptosis." (PMID 37770979, 2023). "In this study, we found that the expression of TTK was positively correlated with the mortality rate of patients with gastric cancer, and high expression of TTK was conducive for tumor recurrence." (PMID 32530571, 2020). "In summary, our data indicate that TTK is involved in the regulation of gastric cancer proliferation and apoptosis." (PMID 32530571, 2020). "By detecting cell proliferation and caspase‐3/7 activities, we found that expression of TTK gene effectively restored the growth rate of gastric cancer cells and inhibited apoptosis." (PMID 32530571, 2020). "TTK was also upregulated in gastric cancer cells and was observed to be essential for the proliferation and survival of gastric cancer cells." (PMID 32530571, 2020). "Our data suggest that TTK is involved in the regulation of gastric cancer proliferation and apoptosis." (PMID 32530571, 2020). "In this study, survival and tumor recurrence data related to TTK expression level in gastric cancer patients were collected and analyzed." (PMID 32530571, 2020). "By analyzing TTK expression in 408 gastric cancer tissues and 211 normal tissues, we found that TTK was extremely upregulated in gastric cancers by about 16‐fold." (PMID 32530571, 2020). "We report here that high TTK expression is correlated with lower survival rate and higher tumor recurrence in gastric cancer patients." (PMID 32530571, 2020). "After siRNA transfection into gastric cancer cells, the mRNA and protein expression of TTK were detected by real‐time PCR and western blotting, respectively." (PMID 32530571, 2020). "Knockdown or inhibition of TTK in gastric cancer cells resulted in Akt‐mTOR dysregulation and enhanced apoptosis of cancer cells." (PMID 32530571, 2020). "To further investigate the specific function of TTK in cells, we examined the expression of TTK in various gastric cancer cells." (PMID 32530571, 2020). "Compared with immortalized gastric epithelial cell line GES‐1, we found that TTK was significantly overexpressed in gastric cancer cell lines HGC‐27 and MGC‐803." (PMID 32530571, 2020).
gastric cancer (continued). "Finally, SGO2, TTK, and CENPF were associated with the acquired chemoresistance to cisplatin and fluorouracil combination chemotherapy in gastric cancer." (PMID 36213825, 2022). "In gastric cancer, TTK activates the Akt-mTOR pathway to regulate cell proliferation and apoptosis." (PMID 36158685, 2022). "Moreover, when TTK protein was decreased, cells underwent apoptosis, indicating that TTK is an oncogene, which is involved in the regulation of gastric cancer tumorigenesis." (PMID 32530571, 2020). "Together, these results indicate that TTK may function as oncogene and be of great importance in the tumorigenesis of gastric cancers." (PMID 32530571, 2020). "TTK expression is elevated in multiple cancers (breast, lung, and gastric cancer)." (PMID 27618721, 2016). "A few genes, such as the receptor tyrosine-protein kinase erbB-3 (ERBB3), which is related to growth factors, and dual specificity protein kinase (TTK), which is related to cell proliferation, were found to be up-regulated in the intestinal gastric cancer samples." (PMID 21435268, 2011). "TTK could be a new marker for the prognosis and potential therapeutic targets of gastric cancer." (PMID 32530571, 2020). "However, in 397 gastric cancer patients who did not have a mutated TTK gene, their mean survival was only 27.33 months." (PMID 32530571, 2020). "The key genes had been validated in GSE14210, and SGO2, TTK, and CENPF have been related with the obtained chemoresistance to cisplatin and fluorouracil mixture chemotherapy in gastric cancer." (PMID 36213825, 2022). "However, the relationship between TTK and the formation of gastric cancer has not been reported in the literature, and its role and molecular mechanism still need further study." (PMID 32530571, 2020). "However, the function of TTK in tumorigenesis has not been extensively studied, especially in relation to the development of gastric cancer." (PMID 32530571, 2020). "However, in addition to the clear study in cell mitosis, TTK protein has not been extensively studied in the specific mechanism of tumorigenesis, especially in the development of gastric cancer." (PMID 32530571, 2020).
hepatocellular carcinoma (18 papers, 2014 to 2026). A malignant tumor that arises from hepatocytes. "Our previous study suggested that TTK is overexpressed in hepatocellular carcinoma (HCC) and its expression is closely associated with clinical outcomes." (PMID 38658569, 2024). "Overexpression of TTK in hepatocellular carcinoma corresponded with hepatitis B surface antigen (HBsAg), age, satellite lesions, and the Edmondson tumor grade." (PMID 34072728, 2021). "In all, our findings suggest that TTK is a potential therapeutic target, especially for human hepatocellular carcinoma." (PMID 24905462, 2014). "In addition, increased expression of TTK in hepatocellular carcinoma tissue compared to normal tissue has also been reported." (PMID 40723362, 2025). "Additionally, TTK expression was elevated in hepatocellular carcinoma tissue compared to normal tissue, and functional studies confirmed TTK’s oncogenic activity." (PMID 38195567, 2024). "Similarly, TTK knockdown in hepatocellular carcinoma inhibited tumor migration, proliferation and cellular activity." (PMID 38195567, 2024). "Collectively, TTK plays an important role in proliferation and sorafenib resistance and could act as a potential therapeutic target for human hepatocellular carcinoma." (PMID 24905462, 2014). "The small molecule Mps1 inhibitors, commonly referred to as TTK inhibitors, CFI-402257, MPI-0479605 and NMS-P715 have been found to reduce tumor growth in hepatocellular carcinoma, lung cancer, ovarian cancer and melanoma xenograft models." (PMID 38596293, 2024). "Cellular immunofluorescence staining and Western blot assays of hepatocellular carcinoma cells in the SAC3D1 knockdown expression group exhibited reduced expression levels of Aurora B and TTK, implying that SAC3D1 knockdown mitigated SAC function dysregulation." (PMID 39100078, 2024). "The results showed that AC099850.3 could promote the migration and proliferation of hepatocellular carcinoma cells in vitro, and RT-PCR experiments found that AC099850.3 could promote the expression of the cell cycle molecules BUB1, CDK1, PLK1, and TTK." (PMID 34123835, 2021).